MMP9 (matrix metallopeptidase 9)
Diseases named in the same sentence as MMP9 in open-access papers (continued):
Sharing a sentence is not in itself a finding about the gene and the disease.
breast carcinoma (continued). "Moreover, integrin-facilitated signal transduction pathways can augment the extracellular activities of MMPs, such as the increase of fibronectin can upregulate the expression of MMP-2 and MMP-9 in human MCF-7 breast cancer cells." (PMID 36910158, 2023). "No other studies have examined the impact of lysicamine on cell migration in cancer cell lines; however, research on apomorphine, another alkaloid, demonstrated its ability to suppress cell invasion, as well as TNF-α-induced MMP9 expression in breast cancer cells." (PMID 38139812, 2023). "MMP-1 secreted by breast cancer cells promotes angiogenesis and bone metastasis, while MMP-9 released by tumor-infiltrating neutrophils and macrophages triggers the angiogenic switch by releasing VEGF from tumor matrix to sustain angiogenesis-driven intravasation and metastasis." (PMID 37350937, 2023). "After MLLT11 knockdown, the invasion ability of MDA-MB-231 breast cancer cells was lowered which might be associated with the decreased levels of MMP2 and MMP9 proteins." (PMID 38075552, 2023). "MMP-9 has also been shown to exert both pro- and anti-tumorigenic roles in breast cancer." (PMID 36741729, 2022). "Serum MMP-9 levels were significantly upregulated in breast cancer patients compared to normal controls and high serum MMP-9 levels were significantly associated with poor prognostic factors, such as higher tumor size and lymph node metastasis, and lower relapse-free survival and OS rates." (PMID 36741729, 2022). "While an increase of KDM3A is concomitant with a reduced H3K9me2/3 during breast tumorigenesis, KDM3A facilitated the activation of genes implicated in breast cancer as MYC, PAX3, Cyclin D1, MMP-9, S100A4, and JUN, thereby enhancing the proliferation and motility of breast cancer cells." (PMID 36185256, 2022). "Additionally, angiogenic factors including VEGFa and MMP9, REST target genes associated with migration and invasion of breast cancer cells, were upregulated in ER- or TNBC tumors." (PMID 35177031, 2022). "In addition, activity of MMPs, known to be related to the EMT process, was analyzed by zymography, and it was observed that LEE reduced the level of MMP-9/2 in breast cancer cell culture medium." (PMID 36077241, 2022). "It decreases lung cancer invasion by inhibiting the S100A4/NF-B/MMP9 axis: 350 reduces both the breast cancer cell pulmonary metastases and metastatic potential of lapatinib-resistant breast cancer cells by inhibiting the STAT3-FAK-Src axis and epithelial-mesenchymal transition (EMT), respectively." (PMID 35225948, 2022). "Another study suggested that differential expression of MMP-9 could contribute to breast cancer heterogeneity to identify different subtypes." (PMID 35586209, 2022). "The αvβ3 integrin activates MMP-2- and MMP-9-dependent pathways in breast cancer metastasis." (PMID 35163668, 2022). "Indeed, the overexpression of MMP9 results in increased production of antiangiogenic fragments, decreased angiogenesis, and therapeutic effects of established breast cancer." (PMID 36497286, 2022). "In breast cancer, elevated expression of MMP9 is a predictor of shorter patient survival." (PMID 36118887, 2022). "IGF-1 has been shown to upregulate the expression of MMP-9 and uPA, as well as MMP-9 activity, in breast carcinoma cells, though this regulation may be cell-type specific." (PMID 36556357, 2022). "Moreover, current studies have shown that DCH can reduce the activity levels of MMPs, particularly MMP2 and MMP9, in breast cancer, glioma, and oral squamous cell carcinoma." (PMID 36408277, 2022). "A meta-analysis comprising 41 studies and 6517 patients with primary breast cancer reported that MMP2 and MMP9 overexpression conferred a higher risk of distant and lymph node metastasis, respectively, and were both associated with higher clinical stage and histological grade." (PMID 36591235, 2022).
breast carcinoma (continued). "In conclusion, the present study revealed, for the first time, the anti-proliferative, apoptotic, anti-migration and EMT inhibition activities of azilsartan against breast cancer cells through modulating NF-kB/IL-6/JAK2/STAT3/MMP9, TWIST/SNAIL/SLUG and apoptosis signaling pathways." (PMID 36431925, 2022). "Nevertheless, surgical resection, even in patients with breast cancer, can increase the expression of MMP-9 and vascular endothelial growth factor (VEGF), which may promote tumor growth and metastasis, as documented in some xenograft models of breast cancer." (PMID 35223475, 2022). "In the present study, we found that circNFIX may act as a ceRNA through regulating MMP9 expression and fatty acid metabolism in breast cancer, which may be a novel mechanism of elevated MMP9 expression." (PMID 35852149, 2022). "Previous ar-turmerone studies on breast cancer showed the inhibition of enzymatic activity and the expression of matrix metallopeptidase 9 (MMP-9) and cyclooxygenase-2 (COX-2) through the nuclear factor kappa-light-chain-enhancer of activated-B-cells (NF-κB) pathway." (PMID 35567007, 2022). "Similarly, in this study too, MMP-9 was predicted to be a critical target of Tamarixetin and furthermore the experimental analysis demonstrated Tamarixetin to inhibit breast cancer cell migration as well as invasion." (PMID 35273218, 2022). "NGAL/MMP-9 complex in urine is a candidate marker for breast cancer, glioma and gastric cancer." (PMID 36010914, 2022). "Studies have also demonstrated the anti-tumorigenic activity of MMP-9 in breast cancer." (PMID 36741729, 2022). "circNFIX and MMP9 may play a unique role by regulating fatty acid metabolism in breast cancer, which suggest a potential therapy in the future." (PMID 35852149, 2022). "Indeed, treatment with curcumin downregulates the expression of TGF-β1 which in turn inactivates molecular MMP-9 and Smad2 fibrotic markers, suppressing the growth of breast cancer cells." (PMID 36143462, 2022). "The activated MMP9 participates in the invasion and metastasis in breast cancer with high grade." (PMID 35081855, 2022). "At this point, we presented that the circNFIX and MMP9 may play a significant role by regulating fatty acid metabolism in breast cancer." (PMID 35852149, 2022). "In vivo, mice injected with miR-429-transfected breast cancer cells had reduced cancer-induced osteolysis when compared to a control, and histological analysis of the bone metastases showed a reduction in both CrKL and MMP-9 expression in the miR-429 group." (PMID 35158995, 2022). "Besides, another study established that leptin elevates the expression levels of Twist and β-catenin, as well as the release of invasion markers MMP-2 and MMP-9 in breast cancer cells, leading to enhanced cell invasion in an SRC- and FAK-dependent way." (PMID 35379785, 2022). "Furthermore, patients lacking these chemokine receptors showed higher expression of VEGF and MMP9, indicating the anti-tumor functions of ACKRs in breast cancer." (PMID 35677043, 2022). "We claim that higher pulmonary endothelium permeability 24 h after i.v. and, consequently, higher levels of Ang-2, E-selectin and MMP-9 2 days after i.v., provided more favourable microenvironemnt for the increased settlement of 4T1 breast cancer cells in the lungs of dabigatran-treated mice." (PMID 35295330, 2022). "The expression level of MMP2 and MMP9 was closely involved in breast-cancer metastasis." (PMID 36497431, 2022). "PAMAM has been grafted on GO to deliver MMP-9 shRNA and miR-21i to breast cancer cells." (PMID 35743245, 2022). "Targeting MMP9 can reduce breast cancer progression and modulates EMT genes." (PMID 36431925, 2022). "Inhibition of MMP-9 expression by microRNA-429 significantly inhibited bone metastasis of breast cancer, which suggested that MMPs may become therapeutic targets for cancer cell metastasis." (PMID 36678509, 2022).
breast carcinoma (continued). "CUR was reported to regulate the metastasis of breast cancer cells via inhibiting MMP-9 and MMP-2." (PMID 36003508, 2022). "The results indicated that the high expression of LINC01615 could promote the expression of MMP9 in breast cancer." (PMID 36230738, 2022). "However, LOX silencing in breast cancer cells by siRNA can downregulate the expression of matrix metalloproteinase 2 (MMP-2) and MMP-9 in breast cancer tissues." (PMID 36293126, 2022). "In the present research, for the first time to our knowledge, the ability of salvianolic acid B, an active compound of Salviae mitiorrhizae, to modulate the function of MMP-9 in human MDA-MB-231 breast cancer cells was demonstrated in an in vitro model characterized by a high invasive potential." (PMID 36500603, 2022). "Interestingly, the expression of MMP-2 and MMP-9 is upregulated in breast cancer, and their expression level is correlated with lymph node metastasis and tumor staging." (PMID 35847867, 2022). "MMP inhibitory monoclonal antibodies targeting MMP-9 or -14 demonstrated promising anti-tumor activities in preclinical models of breast cancer and may exhibit clinical benefits in cancer patients without significant toxicity in clinical trials." (PMID 36741729, 2022). "Therefore, we investigated the effects of UA on invasion and metastasis, ODC-related polyamine metabolism, and MAPK-Erk-VEGF/MMP-9 signaling pathways in a doxorubicin-resistant breast cancer cell (MCF-7/ADR) model." (PMID 35209071, 2022). "Therefore, we further assessed the impact of HMGA1 on PI3K/AKT/MMP-9 pathway in breast cancer cells." (PMID 36479041, 2022). "Here, we obtained the novel findings that SIRT6 is involved in the modulation of breast cancer cell invasion and migration by regulating MMP-9 expression in breast cancer cells, suggesting that SIRT6 is a novel target molecule for the prevention of breast cancer." (PMID 35840633, 2022). "In addition, PELP1could also enhance E2 induced ruffles and filopodium-like structure and up-regulated transcription of MMP-9 in breast cancer cells, resulting in the promotion of the metastasis of the tumor cells." (PMID 34257530, 2021). "Additionally, 15-Delta prostaglandin J2 can suppress NF-κB and AP-1-mediated MMP-9 expression, and invasion of breast cancer cell by means of a heme oxygenase-1-dependent mechanism." (PMID 33796449, 2021). "Similarly, to our results, the simultaneous upregulation of HIF-1α and MMP-9 was described in tumor tissues from patients with breast cancer." (PMID 33920263, 2021). "Other researchers also concluded that altered expression of some genes (RRM2, SPP1, MMP9, Arf1) could be involved in increased cell proliferation of adipose tissue in breast cancer risks." (PMID 34657612, 2021). "Overexpression of SCARA5 downregulated MMP-2, MMP-3 and MMP-9 in breast cancer cell." (PMID 33758617, 2021). "Additionally, it was discovered that MMP9 was differentially expressed within different molecular subtypes of breast cancer." (PMID 34221232, 2021). "In addition, analysis of the RNA-seq data confirmed the obtained results and showed that MMP-9 is overexpressed in the TCGA breast cancer cohort compared to normal tissue." (PMID 34884588, 2021). "Furthermore, calycosin treatment significantly reduced the levels of CD147, MMP-2, and MMP-9 in TGFβ1-overexpressing breast cancer cells." (PMID 34096887, 2021). "In conclusion, we found a new mechanism that DACH1 could inhibit the metastasis of breast cancer cells by inhibiting the expression of MMP9." (PMID 34772908, 2021). "Likewise, the overexpression of MMP9 and CTSD observed in HMECs infected with HCMV-BL was associated with the most aggressive subtype of breast cancer, tumor cell invasion, and metastasis." (PMID 35003089, 2021). "Moreover, MMP-2 and MMP-9 also contribute to epirubicin resistance in non-small-cell lung cancer and breast cancer." (PMID 34654351, 2021).
breast carcinoma (continued). "In addition, the study showed that MMP-9 level varies in different molecular subtypes of breast cancer." (PMID 34884588, 2021). "Furthermore, we evaluated the expression of tumor-promoting genes that play critical roles in the progression and metastasis of breast cancer, such as MMP9, Runx2, TGFβ, and Snail." (PMID 34230453, 2021). "In addition, it has been reported that CO inhibits the phosphorylation of ERK and c-Jun induced by TPA, which inhibits MMP-9 activity on MCF-7 breast cancer cells." (PMID 34483918, 2021). "Recently, MMP-9 has been shown to be required for invasion in breast cancer and osteosarcomas." (PMID 33780455, 2021). "For example, MMP2 and MMP9 were possible tumor markers for breast cancer patients." (PMID 35069702, 2021). "Han and his groups reported that SATB1 upregulated the expression of MMP-9 in breast cancer." (PMID 33390772, 2021). "Recently, the effect of Fis on MMP-2 and MMP-9 expression in triple breast cancer cells (4T1 and JC cells) was investigated, with the findings that Fis reduced cell motility and that this phenomenon was partially associated with a reduction of MMP-2 and MMP-9 expressions." (PMID 33498927, 2021). "In addition, recent work by Egeblad’s laboratory showed that digestion of laminin-111 via MMP9 by neutrophils contributes to the awakening of dormant breast cancer cells." (PMID 34638400, 2021). "It was previously reported that high levels of MMP-9 promote the aggressiveness of breast cancer." (PMID 34884588, 2021). "Inhibition of MMP2 and MMP9 produces anti-metastatic effects in breast cancer and HCC." (PMID 35011007, 2021). "Additionally, a natriuretic peptide receptor, NPRA, increases STAT3 and MMP9 expression, resulting in the induction of breast cancer cells migration and invasion." (PMID 34488773, 2021). "Another possible mediator of the effect of PGRMC1 on breast cancer migration is MMP9, which promotes the colonization of the lungs by inducing metastatic aggressiveness as well as the migration and invasion of cancer cells while not significantly affecting the tumor burden." (PMID 33832499, 2021). "MMP9 has been recognized as a possible biomarker for metastasis in various cancers such as ovarian cancer, non-small cell lung cancer, colorectal cancer and breast cancer." (PMID 34680394, 2021). "Mainly, MMP-2 and MMP-9 are most well-studied in cancer cells since these MMPs are highly secreted in breast cancer cells as a proenzyme before activation through hydrolysis and degrade collagen type-IV basement membrane (BM), which in turns alters the ability of BM to disrupt cancer cell mobility." (PMID 34181339, 2021). "The increased expression of MMP9 is also related to the invasion, metastasis and poor prognosis of different types of cancer, such as cervical cancer, colorectal cancer, ovarian cancer and breast cancer." (PMID 33430865, 2021). "In human primary breast cancer cells from two sources, A5 CM reduced the Runx2 and MMP9 levels." (PMID 34230453, 2021). "In addition to ERK, SPHK1/S1P/S1PR3 axis has been implicated in potentiating the progression of breast cancer through upregulations of C-reactive protein (CRP) and MMP9." (PMID 34820423, 2021). "miR-335 is reported to control MMP9 in glioma, as suggested in breast cancer." (PMID 33673181, 2021). "Our study showed that DACH1 could repress the breast cancer cell metastasis and invasion by inhibiting the expression of MMP9 at the transcriptional level." (PMID 34772908, 2021). "Calycosin significantly increased the expression of E-cadherin (epithelial cell biomarker) and decreased the expression levels N-cadherin and Vimentin (mesenchymal cell biomarkers) as well as CD147, MMP-2, and MMP-9 (pro-metastatic proteins) in the breast cancer cells." (PMID 34096887, 2021). "In turn, MMP-9 expression is significantly increased in breast cancer cells." (PMID 34884588, 2021).
breast carcinoma (continued). "It has been demonstrated that coupling of S1P to S1PR3 can induce CRP expression via CCAAT/enhancer-binding protein β (C/EBPβ), activate Rac1/Nox-4/ROS/ERK pathways, and upregulate MMP9 activity, contributing to the aggressiveness and invasion of breast cancer." (PMID 34820423, 2021). "The results indicate a strong correlation of MMP-9 with CK19 mRNA in breast carcinoma." (PMID 34884588, 2021). "The expression of MMP-9 expression is positively correlated with lymph node metastasis and histological grade of endometrial carcinoma, and negatively correlated with invasion, metastasis and bone metastasis of breast cancer." (PMID 33430865, 2021). "Interestingly, it has been reported that MMP-9 production in breast cancer cells in regulated by PI3K/AKT/NF-κB pathway; therefore, it can be assumed that MMP-9 release by macrophages and neutrophils is also controlled by NF-κB." (PMID 33445783, 2021). "While MMP9 produced by cancer cells drives the development of metastasis in triple negative breast cancer and can promote circulating tumor cells to colonize the lungs in luminal B breast cancer." (PMID 34638400, 2021). "Interestingly, miR-138 and -210 regulate HIF genes, while miR-335 was reported to control MMP9 in glioma and has been suggested to play a role in breast cancer progression." (PMID 33673181, 2021). "Studies have previously demonstrated that MMP9 contributed to breast cancer brain metastasis by promoting cells' trans-endothelial migration and permeability across the blood-brain barrier (BBB), and its expression level was correlated with breast cancer brain metastasis-free survival 22-25." (PMID 34421353, 2021). "MMP-2 and MMP-9 are also involved in each stage of breast-cancer-to-bone metastasis." (PMID 34445715, 2021). "The present study further supported our previous report about the potency of AC and IC as herbals for breast cancer remedies due to their positive action toward MMP9 and four cancer cells, including triple-negative sub-types (MDA-MB-231 and 4T1) as well as luminal A subtype (T47D and MCF7)." (PMID 33800366, 2021). "The current study concluded that the novel ruthenium-fluvastatin complex is capable of downregulating SNCG expression associated with breast carcinoma cell line regulation by inhibiting cell proliferation and inducing apoptosis by triggering the cascade of PI3K/Akt/mTOR/VEGF/MMP9." (PMID 34221232, 2021). "However, the differentiation of PAM50 showed that MMP-9 expression is significantly higher in basal breast cancer compared to the luminal A subtype." (PMID 34884588, 2021). "Next, we tested whether TIMELESS could inhibit the invasion and metastasis of breast cancer via The MMP9 signaling pathway." (PMID 33430865, 2021). "In addition, GE exerts potential anti-metastasis activity by suppressing MMP-9 expression and inhibiting the migration of highly metastatic breast cancer 4T1 cells." (PMID 31983172, 2020). "Moreover, surfactin can inhibit PM-induced cell migration and invasion via inhibition of MMP-2 and MMP-9 expression in various cancer cells including oral cancer cells and breast cancer cells." (PMID 32922544, 2020). "Moreover, astrocyte-derived MMP-2 and MMP-9 have also been shown to promote tumor cell invasion in breast cancer brain metastasis." (PMID 32481745, 2020). "In addition to the S1PR1 axis, IL-22 stimulated the expression of matrix metalloproteinase-9 (MMP-9), thereby promoting breast cancer cell invasion." (PMID 31935914, 2020). "TGF-β/Smad signaling can upregulate MMP2 and MMP9 to induce breast cancer cell invasion." (PMID 32226772, 2020). "Moreover, TNFα activates the MAPK/ERK signaling pathway and subsequently promotes the migration of breast cancer cells through the upregulation of MMP9, MMP14, and MMP2 in the lipid rafts." (PMID 32986377, 2020). "Down-regulation of MMP-9 enhances the overall survivalof patients with breast cancer." (PMID 33095554, 2020).